FBXL2 (F-box and leucine rich repeat protein 2)
Description:
Calcium-activated substrate recognition component of the SCF (SKP1-cullin-F-box protein) E3 ubiquitin-protein ligase complex, SCF(FBXL2), which mediates the ubiquitination and subsequent proteasomal degradation of target proteins. Unlike many F-box proteins, FBXL2 does not seem to target phosphodegron within its substrates but rather calmodulin-binding motifs and is thereby antagonized by calmodulin. This is the case for the cyclins CCND2 and CCND3 which polyubiquitination and subsequent degradation are inhibited by calmodulin. Through CCND2 and CCND3 degradation induces cell-cycle arrest in G(0). SCF(FBXL2) also mediates PIK3R2 ubiquitination and proteasomal degradation thereby regulating phosphatidylinositol 3-kinase signaling and autophagy. PCYT1A monoubiquitination by SCF(FBXL2) and subsequent degradation regulates synthesis of phosphatidylcholine, which is utilized for formation of membranes and of pulmonary surfactant (By similarity). The SCF(FBXL2) complex acts as a regulator of inflammation by mediating ubiquitination and degradation of TRAF proteins (TRAF1, TRAF2, TRAF3, TRAF4, TRAF5 and TRAF6) (By similarity). The SCF(FBXL2) complex acts as a negative regulator of the NLRP3 inflammasome by mediating ubiquitination and degradation of NLRP3. The GGTase-3 complex, composed of PTAR1 and RABGGTB, geranylgeranylates and targets FBXL2 to the cellular membranes, where FBXL2 forms part of the SCF(FBXL2) complex that mediates the degradation of membrane-anchored proteins.
Synonyms: FBL2; FBL3
Tractability: PROTAC: UniProt records ubiquitination sites on it; ubiquitination databases record sites on it; its protein half-life has been measured.
Gene: Protein-coding gene on chromosome 3 (33,277,025 to 33,403,662, forward strand). Ensembl gene ENSG00000153558.
Subcellular location: Membrane
Subcellular location (Human Protein Atlas): Plasma membrane; Nucleoli; Nucleoplasm
Gene Ontology:
Molecular function: phosphatidylinositol 3-kinase regulatory subunit binding; protein binding; protein phosphatase binding; ubiquitin-like ligase-substrate adaptor activity
Biological process: host-mediated perturbation of viral RNA genome replication; negative regulation of NLRP3 inflammasome complex assembly; protein ubiquitination; regulation of autophagy; regulation of phosphatidylinositol 3-kinase/protein kinase B signal transduction; SCF-dependent proteasomal ubiquitin-dependent protein catabolic process; protein modification process; proteolysis; regulation of inflammatory response; regulation of defense response
Cellular component: membrane; plasma membrane; SCF ubiquitin ligase complex; cytoplasm
Genetic constraint (gnomAD): Loss-of-function variants: 30 observed, 58.76 expected, observed/expected ratio (o/e) 0.51, 90% interval 0.38 to 0.69. The upper end of that interval is the gene's LOEUF score, 0.69, which puts it in group 2 of 6, group 1 being the genes least tolerant of losing a copy. Missense variants: 325 observed, 495.45 expected, observed/expected ratio (o/e) 0.66, 90% interval 0.6 to 0.72. Synonymous variants: 177 observed, 196.26 expected, observed/expected ratio (o/e) 0.9, 90% interval 0.8 to 1.02.
Homologues: Orthologues: macaque FBXL2 (99% identical), dog FBXL2 (99% identical), pig FBXL2 (97% identical), mouse Fbxl2 (96% identical), chimpanzee FBXL2 (93% identical), rat Fbxl2 (92% identical), guinea pig FBXL2 (91% identical), zebrafish fbxl2 (81% identical), rabbit FBXL2 (58% identical), Drosophila melanogaster CG9003 (55% identical), Caenorhabditis elegans fbxl-1 (48% identical), Drosophila melanogaster CG8272 (28% identical), and 23 more. Paralogues in human: FBXL20 (78% identical), FBXL13 (26% identical), FBXL7 (25% identical), FBXL18 (22% identical), FBXL4 (22% identical), FBXL5 (22% identical), FBXL14 (21% identical), FBXL16 (21% identical), FBXL6 (21% identical), SKP2 (19% identical), FBXL3 (18% identical), FBXL17 (17% identical), and 3 more.
Diseases named in the same sentence as FBXL2 in open-access papers:
FBXL2 is named in the same sentence as 23 diseases in open-access papers, as found by Europe PMC text mining. Sharing a sentence is not in itself a finding about the gene and the disease. The quoted sentences say what the papers report.
colorectal cancer (2 papers, 2021 to 2022). A primary or metastatic malignant neoplasm that affects the colon or rectum. "Another study showed that miR-597 promoted colorectal cancer cell proliferation in vitro and in vivo by targeting FBXL2 and activating the β-catenin signaling pathway." (PMID 34458365, 2021). "It has been shown that FOSL1 can promote the development and invasion of colorectal cancer through the Smurf1-mediated FBXL2/Wnt/β-catenin axis and the migration, invasion, and proliferation of breast, head, and neck squamous cell carcinoma, pancreatic cancer, bladder cancer, and prostate cancer." (PMID 36061185, 2022).
leukemia (2 papers, 2018 to 2024). A malignant (clonal) hematologic disorder, involving hematopoietic stem cells and characterized by the presence of primitive or atypical myeloid or lymphoid cells in the bone marrow and the blood. "Moreover, FUNDC1 up-regulation reduces FBXL2 ubiquitination, thus maintaining FBXL2 protein expression in leukemia." (PMID 38947217, 2024). "By inducing FBXL2, FUNDC1 reduces ferroptosis in leukemia through the inhibition of mitochondrial damage." (PMID 38947217, 2024). "In a leukemia model, FUNDC1 up-regulation induces the expression of FBXL2." (PMID 38947217, 2024). "In addition, the E3 ligase family members Fbxl2, Fbxl10, and SKP2 participate in the proliferation of leukemia cells by regulating the ubiquitination pathway." (PMID 29555946, 2018). "The E3 ligases Fbxl2, Fbxl10, and SKP2 participate in the proliferation of leukemia cells." (PMID 29555946, 2018).
lung carcinoma (2 papers, 2021). "The expression of EGFRL858R/T790M mutant protein is frequently found in lung cancer patients, we then investigated the effects of FBXL2 on the growth of EGFRL858R/T790M-driven NSCLC in vitro and in vivo." (PMID 34635651, 2021). "Indeed, ubiquitin-mediated degradation of CCND3 by FBXL2 has been demonstrated in lung cancer, while in breast cancer cells, the RNA-binding protein IMP-3 can regulate CCND3 protein expression by directly binding to its mRNAs." (PMID 34440000, 2021).
atherosclerosis (1 paper, 2022). A disease characterized by the build-up of fatty material and calcium deposition in the arterial wall resulting in partial or complete occlusion of the arterial lumen. "Moreover, FBXO3 is known to stimulate cytokine secretion by destabilizing FBXL2 through UPS, and exert its pro-inflammatory effect in a variety of disease models including lung I/R injury, pneumonia, sepsis, and atherosclerosis." (PMID 36362432, 2022).
gastric cancer (1 paper, 2020). A primary or metastatic malignant neoplasm involving the stomach. "Fbxl2 can be modified by O-GlcNAcylation, which suppresses the Fbxl2-mediated degradation of FOXM1 and contributes to gastric cancer pathogenesis." (PMID 33234069, 2020).
glioblastoma (1 paper, 2020). The most malignant astrocytic tumor (WHO grade IV). "Particularly, we found that ALZ003 induces FBXL2-mediated AR ubiquitination, leading to downregulation of AR in glioblastoma." (PMID 31896509, 2020). "Importantly, FBXL2 knockdown significantly attenuated ALZ003-induced cytotoxicity, further suggesting that ALZ003 suppresses the growth of glioblastoma through inducing FBXL2-mediated AR ubiquitination." (PMID 31896509, 2020).
liver cancer (1 paper, 2020). An epithelial or non-epithelial malignant neoplasm that arises from the liver. "Moreover, miR-346 also serves as a cancer-promoting gene, which can facilitate the proliferation, invasion and metastasis of liver cancer cells through targeted inhibition on F-Box and leucine-rich repeat protein (FBXL2)." (PMID 31966062, 2020).
lung adenocarcinoma (1 paper, 2021). A carcinoma that arises from the lung and is characterized by the presence of malignant glandular epithelial cells. "Moreover, clinical analyses of TCGA database revealed low expression of FBXL2 and high expression of Grp94 in lung adenocarcinoma (LUAD) or lung squamous cell carcinoma (LUSC)." (PMID 34635651, 2021). "TMA analyses showed that FBXL2 was progressively reduced during lung adenocarcinoma development." (PMID 34635651, 2021). "We further examined FBXL2 expression at various stages of human lung adenocarcinoma (LUAD)." (PMID 34635651, 2021). "Furthermore, a reverse correlation was observed between FBXL2 and EGFR protein expression in TMA of lung adenocarcinoma and lung squamous cell carcinoma." (PMID 34635651, 2021).
lung squamous cell carcinoma (1 paper, 2021). "In addition, analyses of tissue microarrays (TMA) showed that low levels of FBXL2 expression were observed in 66.67% (50 of 75) in human lung squamous cell carcinoma (LUSC) compared to adjacent tissues." (PMID 34635651, 2021).
Obesity (1 paper, 2023). Accumulation of substantial excess body fat. "Evidence show that FBXL2, a protein of the same family, preserves cardiac homeostasis in the face of HFD-induced obesity." (PMID 37252693, 2023).
Parkinson disease (1 paper, 2021). A progressive degenerative disorder of the central nervous system characterized by loss of dopamine producing neurons in the substantia nigra and the presence of Lewy bodies in the substantia nigra and locus coeruleus. "Therefore, in view of the importance of the F-box domain in the interaction with DAT, we studied the possible association of the transporter with other F-box proteins that have been implicated in Parkinson disease (such as FBXO7 or FBXO18) or in the stability of FBXL2 (such as FBXO3)." (PMID 34709416, 2021).
viral infection (1 paper, 2021). "SCFFBXL2 regulates the protein stability of TRAF proteins in viral infection; mutations in FBXL2 may impair TRAF protein stability that augments inflammatory response." (PMID 34480022, 2021).
tumor (15 papers, 2013 to 2025). "It is important to note that FBXL2 has been previously implicated in cancer, but rather acting via the suppression of cell cycle progression and proliferation, as observed in lung tumors 43, leukemic cells 44, gastric cancer cells 45, and prevalently of tumor suppressive nature." (PMID 31225437, 2017). "In particular, losses have been detected located on chromosomes 3p, 4, and 7q, and, interestingly, the unique genes with roles in tumour-related process in these regions (FBXL2, ROBO2) are tumour suppressors." (PMID 36289850, 2022). "P silencing of Grp94 significantly augmented FBXL2-mediated suppression of H1975 xenograft tumor growth." (PMID 34635651, 2021). "Together, these results demonstrate that nebivolol is a FBXL2 activator that acts to inhibit TKI-resistant tumor growth, which is augmented by ganetespib." (PMID 34635651, 2021). "Our results strongly support the notion that FBXL2 is a tumor suppressor through targeting and promoting EGFR degradation, consequently leading to inhibition of EGFR downstream signaling and suppression of tumor growth." (PMID 34635651, 2021). "It is notable that HLALOH occurred in the samples with recurrent mutations of S-C clonal pattern including KRAS, SYNE1, FBXL2, DNAH11 and CACNA1H, indicating this mutational clonal patter is facilitating tumor cell to escape immune monitor." (PMID 34453042, 2021). "Firstly, FBXL2-mediated inhibition of cell proliferation and tumor growth can be completely rescued by restoration of EGFR expression." (PMID 34635651, 2021). "Potential tumor suppressor activities of FBXL2 utilizing the ubiquitin-mediated degradation of crucial cell cycle regulators have been reported." (PMID 33415077, 2020). "Instead, in this work, the effects of FBXL2 on IP3R3 are tumor promoting by increasing IP3R3 degradation and making the cells more resistant to cell death." (PMID 31225437, 2017). "Given the known role of FBXL2 as a tumor suppressor gene in various tumors, we focused on FBXO5." (PMID 38212299, 2024). "We next investigated whether the effects of Grp94 on cell proliferation and NSCLC tumor growth is dependent on FBXL2." (PMID 34635651, 2021). "Vice versa, the previously discovered tumor suppressive properties of FBXL2 in cancer might be further boosted if FBXL2 could be selectively/subcellularly activated to pro-mote its cell-cycle targets while shielding IP3R3 for degradation." (PMID 31225437, 2017). "In addition, we show that curcumin can significantly inhibit tumor growth via CaM downregulation and that combining curcumin with FBXL2 activator nebivolol markedly inhibits EGFRT790M/C797S expression and overcomes EGFRT790M/C797S-mediated osimertinib resistance in xenograft mouse model." (PMID 40447190, 2025). "In a recent study, inhibition of FBXL2 may also promote apoptosis and limit tumor growth in PTEN-null cancers where PTEN has been identified as a counteractor of FBXL2 in binding with IP3R3 (a major player in Ca+ dependent apoptosis) for ubiquitin mediated degradation." (PMID 32226545, 2020). "FBXL2 (F-Box and leucine rich repeat protein 2), an F-box protein member of the SCF E3 ligase family, displayed anti-tumor activity and its expression is suppressed in AML and ALL patient samples." (PMID 32674429, 2020). "Potential tumor suppressor genes GAS7, RGS6, ADAM11 and FBXL2 are up-regulated in the lesser aggressive group L." (PMID 29844869, 2018). "Many F-box proteins such as FBXW7, FBXL2, FBX4 and FBXO11 are found to be lost in a wide range of human cancers, and generally considered as tumor suppressor genes." (PMID 23826080, 2013). "In addition, two tumour suppressor genes have been lost in the transformed HEK293T, namely FBXL2, able to induce cell cycle arrest, and ROBO2, which inhibits PDAC cell proliferation, migration, and invasion." (PMID 36289850, 2022).
tumor (continued). "In addition, silencing of EGFR significantly rescued FBXL2 knockdown-induced tumor growth in H292 xenograft mouse model, indicating that silencing of FBXL2 promotes NSCLC cell proliferation and tumor growth via up-regulation of EGFR expression." (PMID 34635651, 2021). "Moreover, nebivolol significantly inhibited cell proliferation and tumor growth in PC-9 xenograft mouse model, while it failed to do so upon silencing of FBXL2." (PMID 34635651, 2021). "Furthermore, wild-type FBXL2, but not FBXL2C420S, significantly suppressed tumor growth in H292 xenograft mouse model." (PMID 34635651, 2021).
cancer (7 papers, 2013 to 2021). A tumor composed of atypical neoplastic, often pleomorphic cells that invade other tissues. "Analyses of TCGA database revealed that FBXL2 expression was significantly reduced in NSCLC, even in the cancer samples harboring EGFR gene mutations." (PMID 34635651, 2021). "The biological function of FBXL2 seems to be complex with regard to cancer development." (PMID 34635651, 2021). "We found that PTEN competes with FBXL2 for IP3R3 binding, and the FBXL2-dependent degradation of IP3R3 is accelerated in Pten−/− mouse embryonic fibroblasts and PTEN-null cancer cells." (PMID 28614300, 2017). "Nevertheless, the anti-cancer properties of FBXL2 activators like the small molecule BC-1258 46 will be adversely impacted by FBXL2-mediated IP3R3 degradation, likely limiting their application to PTEN-positive cancers." (PMID 31225437, 2017). "In any case, by inhibiting FBXL2’s action on IP3R3 without inhibiting its action on cell cycle targets could be an attractive avenue to restore IP3R3 levels in these cancers." (PMID 31225437, 2017). "In cancer cells lacking PTEN, FBXL2 knockdown could therefore restore IP3R3 levels and apoptotic sensitivity." (PMID 31225437, 2017).
FBXL2 also shares sentences with these, for which no sentence is quoted: bladder cancer (1 paper); breast carcinoma (1); childhood leukemia (1); glaucoma (1); ischemic stroke (1); pancreatic cancer (1); pneumonia (1); prostate carcinoma (1); Sepsis (1).